CD36 (CD36 molecule (CD36 blood group))
Diseases named in the same sentence as CD36 in open-access papers (continued):
Sharing a sentence is not in itself a finding about the gene and the disease.
melanoma (86 papers, 2002 to 2026). A malignant, usually aggressive tumor composed of atypical, neoplastic melanocytes. "Here we observed that loss of CD36 significantly reduced the ability of melanoma cells to bind to the laminin substrata while retaining full binding capacity to collagen I, collagen IV and fibronectin." (PMID 34215227, 2021). "In melanoma cells, the association between CD36 and b1 integrins requires the extracellular domain of the CD36 molecule." (PMID 24009511, 2013). "An association between integrins and CD36 has been described in several human cell types, including melanoma cells, microglial cells, platelets, and HDMEC." (PMID 24009511, 2013). "Our study indicates that the overexpression of CD36 is associated with decreased progression-free survival in melanoma, and the cancer hallmark enrichment dataset shows that CD36 is associated with reprogramming energy metabolism and tissue invasion or metastasis." (PMID 39062552, 2024). "However, this specific association between dietary fat, CD36 and metastasis remains to be tested in melanoma." (PMID 32549336, 2020). "High expression of the surface protein CD36, the transcription factors Early Growth Response Protein 1, Cyclin D1, and L-Myc and of the enzyme ChAT have been linked to tumor progression, poor survival and increased metastasis in several cancers, including melanoma and recently also in lymphoma." (PMID 36831273, 2023). "A potential mechanism by which this interaction may occur is via a lateral association with integrins, specifically the laminin binding integrins α3β1 and α6β1 both of which have been reported to associate with CD36 in human melanoma cells for enhanced migration on ECM components." (PMID 34215227, 2021). "Melanoma cells also acquire lipids from the microenvironment, particularly from adipocytes, Via transporters such as FA translocase (FAT/CD36), plasma membrane-associated FA binding proteins (FABP) or FA transport proteins (FATP CD36)." (PMID 41596686, 2026). "Clinical evidence shows a decreased levels of CD36 expression in long-term surviving melanoma and multiple myeloma patients, validating this process." (PMID 40855044, 2025). "Taken together, these results show PC is more abundant in the young TME, is taken up via CD36 by melanoma cells where it drives PI3K via pmTORC2, OXPHOS, and ROS." (PMID 40280124, 2025). "Blocking fatty acid uptake via the CD36 receptor inhibits melanoma metastasis; and we show CD36 inhibition additionally blocks PC uptake, PI3K activation and OXPHOS, leading to fewer metastases." (PMID 40280124, 2025). "For this, we tracked PC uptake in melanoma cells treated with a CD36 inhibitor (salvianolic acid B, CD36i), which confirmed that inhibition of CD36 abrogates Cy5-PC uptake, melanoma proliferation and ROS production." (PMID 40280124, 2025). "CD36 has been linked to angiogenesis, apoptotic resistance, and poor outcomes; notably, its upregulation has been observed in MAPK inhibitor–resistant melanoma cells, facilitating drug tolerance." (PMID 40659866, 2025). "The macrophage polarization assay provides evidence that the CD36 cargo in the melanoma EVs determines the fate of immunosuppression in the macrophages." (PMID 39062552, 2024). "This suggests melanoma-derived EVs’ mRNA and cargo proteins can regulate CD36 expression in target cells in response to EV challenge." (PMID 39062552, 2024). "CD8+ T cells infiltrating mouse melanoma B16 or colorectal MC38 tumors uptake oxidized low-density lipoprotein (OxLDL) in a CD36-dependent manner, consequently triggering lipid peroxidation." (PMID 38844964, 2024). "Long-surviving melanoma patients and multiple myeloma patients exhibit reduced CD36 expression on CD8+ T cells and demonstrate responsiveness to programmed cell death 1 (PDCD1, also known as PD-1) treatment." (PMID 38844964, 2024). "A melanoma-cell-line-based EV analysis also indicated the presence of CD36 cargoes in the form of mRNA and proteins." (PMID 39062552, 2024).
melanoma (continued). "We used nanoscale flow cytometry and analyzed the %CD36 in total LEVs from melanoma patients and control." (PMID 39062552, 2024). "We also re-analyzed the macrophage polarization of EVs collected from siRNA-directed CD36-silenced melanoma cells to observe the polarization effect with CD36 carrying EVs versus non-CD36 carrying EVs." (PMID 39062552, 2024). "The lipid content secreted by melanoma directs the transformation of monocytes to tumor-promoting macrophages by altering the lipid metabolism via the upregulation of CD36." (PMID 39062552, 2024). "We detected a decrease in the combined CD163 and CD206 expression in the macrophages treated with EVs from CD36-siRNA-transfected melanoma cells compared to EVs from NTC-transfected melanoma cells." (PMID 39062552, 2024). "We found that melanoma patients who had a high CD36 expression in the tumors progressed significantly sooner than patients whose expression of CD36 falls in the lower quartile (log-rank test statistics = 3.817, p = 0.05)." (PMID 39062552, 2024). "CD36 serves as an important target for melanoma as it overexpresses in drug-tolerant cells of BRAF or MEK therapies." (PMID 39062552, 2024). "Our colocalization modeling of MxIF data to investigate the connection of CD36 with immunological markers provided insight into the deregulation of CD36 with immune cells in subsets of different SLNs of melanoma." (PMID 39062552, 2024). "A recent study showed that CD36 levels were downregulated in cytotoxic CD8+ cells from melanoma patients responding to anti-PD1 treatment." (PMID 39624081, 2024). "Further, we also found that the lymphatic fluid of SLN-afferent tubules from melanoma patients carries more CD36 cargoes in LEVs than in control subjects." (PMID 39062552, 2024). "Melanoma-cell-secreted EVs are capable of enriching CD36 in recipient myeloid cells, leading to immunosuppression." (PMID 39062552, 2024). "Our findings show that cutaneous melanoma patients have a worse clinical prognosis with high CD36 levels, and a higher percentage of CD36 in total LEVs were found at baseline in melanoma patients compared to control." (PMID 39062552, 2024). "A TCGA melanoma cohort research reveals that melanoma patients with high CD36 expression have a worse clinical prognosis." (PMID 38370376, 2024). "A monoclonal antibody targeting CD36 was demonstrated in a melanoma xenograft mouse model, which specifically blocks the uptake and metabolism of fatty acids." (PMID 39000453, 2024). "Our data show that the melanoma cell’s (SKMEL28) EV-mediated CD36 downregulation affects the THP1 cell polarization." (PMID 39062552, 2024). "In a mouse melanoma model, inhibiting CD36-mediated lipid transport effectively eliminated Tregs, leading to suppressed tumor growth without causing systemic immune instability." (PMID 39000453, 2024). "To identify the clinical significance of CD36 expression in melanoma, we analyzed the progression-free survival (PFS) in the SKCM dataset, choosing the upper and lower quartiles of CD36 expression." (PMID 39062552, 2024). "We also found that monocytic and endothelial cells treated with melanoma EVs expressed more CD36 than untreated cells." (PMID 39062552, 2024). "Our present study has provided evidence that melanoma-derived EVs can upregulate the CD36 expression in the recipient cells." (PMID 39062552, 2024). "Together, these data revealed a distinct peroxisome/UGCG-dependent mechanism of tolerance in the MAPKi-induced CD36+ melanoma persister cells." (PMID 37616051, 2023). "To summarize, increased peroxisomal/AGPS activity and UGCG occur in a significant proportion of relapsed melanomas, which are likely driven through the CD36+ drug-tolerant SMC state." (PMID 37616051, 2023). "Cotargeting PEX3 and UGCG selectively eliminated a subset of metabolically active, drug-tolerant CD36+ melanoma persister cells, thereby sensitizing melanoma to MAPKis and delaying resistance." (PMID 37616051, 2023).
melanoma (continued). "This has been observed in mice models of colorectal cancer, melanoma, and glioblastoma, where upregulation of CD36 in Treg cells promotes lipid metabolism under environmental stresses." (PMID 37700339, 2023). "In BRAF-mutant melanoma, CD36 was found to be the most consistently upregulated cell surface marker following MAPK inhibition." (PMID 37371076, 2023). "Dual blockade of PEX3 and UGCG effectively eliminated CD36+ cells, leading to a dramatic induction of apoptosis in MAPKi-treated melanoma cells and improved response to MAPKi and PFS in our preclinical models." (PMID 37616051, 2023). "Together, these data highlight the significance of combining small molecules that disrupt PEX3-PEX19 binding and UGCG inhibitors to target CD36+ persister melanoma cells." (PMID 37616051, 2023). "Most of the enzymes associated with fatty acid synthesis (e.g., FASN, SCD, ACC, ACLY), and receptors related to lipid uptake (e.g., FAT/CD36, FATPs, and FABPpm) are upregulated in several cancers, including melanoma." (PMID 35406721, 2022). "Altogether, these observations suggest that a therapeutic strategy that combines SCD inhibition and CD36 blockade would be very effective to refrain phenotypic plasticity in melanoma." (PMID 35406721, 2022). "Promoting oral cancer or melanoma metastasis in mice, by using palmitic acid diet, involves the mediation of CD36." (PMID 36354702, 2022). "Like what happens to CD8 T cells in PDAs, lipid uptake through CD36 induces terminal exhaustion and is associated with PD-1 and TIM-3 expression and decreased production of IFN-γ and TNF-α in CD8 T cells from B16 melanomas." (PMID 34983949, 2022). "In prostate cancer and melanoma, the membrane transporters CD36 and FATP1 respectively promote lipid accumulation and tumor progression." (PMID 35764645, 2022). "PA also improves the metastatic ability of CD36+ metastasis‐initiating oral cancer cells and promotes proliferation and invasiveness of melanoma." (PMID 35735113, 2022). "Another study demonstrated that TME’s poly-unsaturated FAs taken up by melanoma-infiltrating CD8+ T cells through CD36 provoke lipid peroxidation and ferroptosis, and thereby impair anti-tumor capacities." (PMID 35945203, 2022). "Specific-CD36 depletion in melanoma- or lung tumor-infiltrating CD8+ T cells increases their anti-tumoral potential by stimulating production of cytotoxic cytokines and inhibiting ferroptosis." (PMID 35945203, 2022). "Along the same lines, metastasis-initiating cells in melanoma and other cancer types show as a common feature the overexpression of CD36." (PMID 35912100, 2022). "Treg cells located in melanoma tumors have upregulated CD36 expression and enhanced FA uptake compared with Treg cells from other tissues." (PMID 36568966, 2022). "PA-mediated CD36 overexpression induces epigenetic remodeling of melanoma cells that triggers the secretion of specific pro-neuroregenerative extracellular matrix from intratumoral Schwann cells, disruption of which blocks metastasis initiation." (PMID 35912100, 2022). "Another example is the overexpression of CD36 in Treg cells in melanoma, which favors the dysfunction of TIL." (PMID 36568966, 2022). "To confirm the protective role of CD36 deficiency, we evaluated liver metastasis with different types of tumor cells, including the murine B16F10 melanoma cells, Hepa1-6 hepatoma cells and CT26 colon carcinoma cells." (PMID 36184646, 2022). "For example, the BRAFV600E melanoma cells increase their CD36 cell-surface levels and PPARα-dependent FAO to overcome the MAPK inhibitor effects." (PMID 35945203, 2022). "LPL, CD36, FATP1 (SLC27A1), and FATP2 (SLC27A2), implicated in increased FA uptake into melanoma cells, are unaffected by point mutation in cancer and display gene amplification in 2%–8% of cases." (PMID 35732120, 2022).
melanoma (continued). "Data obtained from The Cancer Genome Atlas (TCGA) was used to determine the significance of CD36 gene expression in the survival of patients with melanoma (TCGA-SKCM project, n = 470)." (PMID 34215227, 2021). "Our observation of CD36-knockdown melanoma cells exhibiting reduced adhesion to laminin concurs with a study by Ladanyi and colleagues who demonstrated that ovarian cancer cells utilize CD36 for adhesion to laminin." (PMID 34215227, 2021). "Using in vitro ‘angiogenesis’ assays and CD36-knockdown approaches, we reveal that CD36 supports VM formation by human melanoma cells as well as adhesion to, and invasion through, a cancer derived extracellular matrix substrate." (PMID 34215227, 2021). "Here we reveal that like CD36, blocking integrin-α3 on melanoma cells inhibited the binding of melanoma cells to laminin in vitro." (PMID 34215227, 2021). "In parallel, the remaining melanoma cells undergo a fatty acid oxidation-dependent metabolic shift, resulting in a short-term emergence of drug-tolerant CD36+ SMC populations." (PMID 34604096, 2021). "In silico analysis of CD36 expression within the melanoma cohort of The Cancer Genome Atlas suggests that melanoma patients with high expression of CD36 have a poorer clinical outcome." (PMID 34215227, 2021). "More specifically, using the in vitro angiogenesis assay with two human melanoma VM-competent cell lines, we observed that knockdown of CD36 by siRNA significantly perturbed VM formation." (PMID 34215227, 2021). "A clear functional role for CD36 in melanoma metastasis has also been demonstrated in preclinical mouse models, whereby the ability of melanoma cells to metastasise was significantly impaired by CD36 depletion." (PMID 34830962, 2021). "Supporting this clinical observation, depletion of CD36 reduces propensity of melanoma cells to metastasize in immune compromised mice." (PMID 32549336, 2020). "The addition of phorbol 12-myristate 13-acetate downregulated TSR-mediated Src recruitment to CD36 on the surface of melanoma cells, suggesting that CD36 is required for TSR-mediated src recruitment to THBS1/L-TGF-β1 signaling pathway 28,29." (PMID 32174800, 2020). "Further work involving lipid transporters such as CD36 or FATP is required to assess if this dependency in BRAF-mutant melanoma is based on lipid uptake or biogenesis processes." (PMID 31819183, 2020). "The field isolate clone MOA C3 transcribed PFGA01_060022400 in a very stable fashion yet it was not possible to increase the low binding capacity of the strain to human melanoma cells expressing recombinant CD36." (PMID 32471507, 2020). "The slow-cycling melanoma subpopulation display highly invasive properties, in part related to the high Serpin 2 and CD36 expression." (PMID 29156643, 2017). "Expression of CD36 on C32 melanoma cells was verified by fluorescence microscopy, after staining with an anti-CD36 antibody showing an intense staining evenly spread over the surface of the cell." (PMID 27296675, 2016). "In contrast, CD36, a molecule known to increase the migration of melanoma cells treated with laminin and fibronectin, was expressed at higher levels in skin than mucosa." (PMID 25198578, 2014). "Growth of Lewis Lung Carcinoma (LL2) and B16F1 Melanoma tumor cell implants in syngeneic wild type (WT), hrg, or cd36 null mice were used as a model to interrogate this signaling axis." (PMID 22808089, 2012). "We therefore repeated our experiments using C32 amelanotic melanoma cells, which endogenously express human CD36." (PMID 18582374, 2008). "CD36, another FA transporter, is highly expressed in metastasis-initiating melanoma cells and correlates with poor prognosis, emphasizing the key role of FA uptake in melanoma progression." (PMID 41596686, 2026). "Additionally, high expression of the CD36 membrane-bound exogenous lipid transporter enables melanoma cells to absorb dietary lipids, promoting metastasis." (PMID 40539068, 2025).
melanoma (continued). "Fatty acids can enter cancer cells from the extracellular space via the CD36 receptor, so we tested whether CD36 mediates PC entry into melanoma cells." (PMID 40280124, 2025). "In addition, cholesterol in TME can regulate CD36 expression up-regulation in mice melanoma B16 and mice multiple myeloma infiltrating CD8+T cells and activate the uptake of fatty acids like AA." (PMID 40855044, 2025). "Inhibition of CD36 expression suppresses melanoma metastasis and improves patient prognosis." (PMID 40539068, 2025). "Furthermore, young-MFP-melanomas expressed higher levels of FABP4, CPT1a, and CD36 than aged-MFP-melanomas validating that the young-MFP is an environment that enhances lipid metabolism in melanoma cells." (PMID 40280124, 2025). "Furthermore, THP1 and HLEC cells were treated with melanoma-derived EVs for 24 h, and we detected the upregulation of CD36 for both human monocytic-THP1 and human LN endothelial cells with an approximately two- to five-fold change." (PMID 39062552, 2024). "Our work further supports the notion that LN macrophages are central to the generation of a premetastatic niche in the SLN, which could be facilitated by melanoma EV-based activation and CD36 overexpression." (PMID 39062552, 2024). "We first determined whether EVs of melanoma patients and the respective control from lymphatic fluid alter the expression of CD36." (PMID 39062552, 2024). "EVs from these melanoma cells showed evidence of CD36 mRNA cargo." (PMID 39062552, 2024). "A melanoma patient’s LEVs carry significantly higher CD36 cargoes compared to a control human LEVs." (PMID 39062552, 2024). "Given the significance of CD36 in its involvement in premetastatic niche development and cancer cell metastasis, a new therapy line against CD36 could directly impact melanoma care." (PMID 39062552, 2024). "In vitro data showed that melanoma-derived EVs could substantially upregulate CD36 expression in monocytic and endothelial cells." (PMID 39062552, 2024). "CD36 expression was analyzed as a higher observed proportion in the melanoma SLNs than normal LN." (PMID 39062552, 2024). "Moreover, cholesterol present in the tumor microenvironment induces the upregulation of CD36 expression in mouse melanoma B16 and mouse multiple myeloma tumor-infiltrating CD8+ T cells, facilitating fatty acid (such as arachidonic acid) uptake." (PMID 38844964, 2024). "Furthermore, challenging EV-derived CD36-intact melanoma cells and CD36-silenced immune cells revealed a difference in total CD36 levels in EV-challenged THP1 cells." (PMID 39062552, 2024). "Furthermore, melanoma-derived EVs can regulate immunosuppressive macrophage-like characteristics by upregulating CD36." (PMID 39062552, 2024). "There is also a possibility that melanoma-derived EVs may contain some other regulatory component that can modulate the expression of CD36 in targeted cells." (PMID 39062552, 2024). "In the spatial regression model comparing the CD36 expression across groups, cells from melanoma SLN (+) were found to have higher odds of expressing CD36 compared to cells from SLN (−) and normal LN (OR = 1.45 and 1.06, respectively), but these comparisons were not statistically significant." (PMID 39062552, 2024). "CD36 is a scavenger receptor that acts as a signaling receptor and a fatty acid transporter known to be involved in the progression of many cancers, including melanoma." (PMID 39062552, 2024). "Martini and colleagues identified CD36 as a regulator of vascular mimicry (VM) in melanoma cells." (PMID 38370376, 2024). "This suggests that melanoma cells synthesize more CD36 to prepare the SLN “soil” for metastasis." (PMID 39062552, 2024). "Importantly, our work revealed a distinct metabolic rewiring mechanism harnessed by a different subset of melanoma cells, namely the CD36+ SMCs, to mediate their tolerance to MAPK-targeted therapies." (PMID 37616051, 2023). "Combined BRAFi/MEKi treatment significantly increased the CD36+ melanoma population." (PMID 37616051, 2023).